RAC1 (Rac family small GTPase 1)
Diseases named in the same sentence as RAC1 in open-access papers (continued):
Sharing a sentence is not in itself a finding about the gene and the disease.
breast carcinoma (continued). "Rac1 has been shown to be overexpressed in lapatinib-resistant HER2 type breast cancer and is considered to be a viable therapeutic for sensitization of lapatinib resistant tumors." (PMID 32322580, 2020). "Similar to studies with Rac1, inhibition of Cdc42 activation by RNAi or expression of a dominant-negative mutant reduced the ability of breast cancer cells to form lung metastatic foci." (PMID 32992837, 2020). "To gain insight into the role of RAC1 in breast cancer, we first performed a comprehensive analysis of the expression of RAC1 in breast cancer tissue samples." (PMID 33298895, 2020). "In Kaplan–Meier plotter survival analysis, the overexpression of RAC1 and RRM2 were shown to be associated with an unfavorable prognosis in HER-2 positive breast cancer patients." (PMID 31895772, 2020). "Another study found that ERK activation via a member of small G proteins Rac1 increases nucleotide metabolism in breast cancer cells and protects against chemotherapy-induced cytotoxicity and DNA damage." (PMID 33096815, 2020). "Our results showed that derivative 4F reduced the luciferase activity of Rac1 in a dose-dependent manner, which means derivative 4F can practically inhibit Rac1 promoter activity in breast cancer cells." (PMID 32547389, 2020). "Together, these results demonstrate that Rac1 activation plays a critical role in regulating trastuzumab resistance in breast cancer." (PMID 32992837, 2020). "Applying the pH-responsive nanoparticle that co-encapsulate Rac1 siRNA and cisplatin provided us a promising translational strategy to sensitize breast cancer to chemotherapies." (PMID 32193458, 2020). "The present study further investigated the inhibitory effect of derivative 4F on breast cancer cell proliferation, invasion, and metastasis in vitro and explored its mechanisms, especially the regulation of Rac1 protein expression." (PMID 32547389, 2020). "RAC1’s anti-apoptotic role has been observed in breast cancer, melanoma, non-small cell lung cancer (NSCLC), colorectal cancer (CRC), head and neck squamous cell cancer (HNSCC), and many others." (PMID 32545340, 2020). "We also found that miR-205 expression inhibited invasion through Matrigel, further confirming the oncogenic role of Rac1 in breast cancer cell migration and invasion." (PMID 32992837, 2020). "Here, we identify the axis ZNF750/RAC1 as a potential novel prognostic biomarker for predicting clinical outcome in breast cancer." (PMID 33298895, 2020). "More importantly, we found a significant upregulation of RAC1 in human breast cancer datasets and we identified a direct correlation between RAC1 expression and the survival rate of breast cancer patient." (PMID 33298895, 2020). "Fgd5 has a DH domain similar to Trio with preferential activation of Rac1, and has been related to poorer prognosis in breast cancer patients." (PMID 32322580, 2020). "In agreement, ZNF750 expression negatively correlates with RAC1 expression in human breast cancer and in particular in luminal A subtypes." (PMID 33298895, 2020). "In our study, RAC1 was found to be upregulated in HER-2 positive breast cancer, while it was interacted more with the downregulated genes." (PMID 31895772, 2020). "Knockdown of Rac1 expression decreases the resistance to chemotherapeutic drugs in breast cancer cells and tumors." (PMID 32193458, 2020). "As a control for the inhibitors, we measured the activation of Rac1 by the ErbB3 ligand heregulin-1 (HRG) in MCF-7 breast cancer cells, a response known to be dependent on P-Rex1 activity." (PMID 32092966, 2020). "Together, these results suggested that Rac1 overexpression conferred resistance to chemotherapy in breast cancer cells." (PMID 32193458, 2020). "E.g., RAC1 is activated by IR and the inhibition of RAC1 abrogates G2 checkpoint activation and cell survival following IR in breast cancer cells." (PMID 32411607, 2020).
breast carcinoma (continued). "In keeping with ZNF750 controlling RAC1 expression, we found an inverse correlation between ZNF750 and RAC1 in human breast cancer datasets." (PMID 33298895, 2020). "Our bioinformatics analysis and in vitro experiments revealed that PODXL2 plays an oncogenic role in breast cancer development via the Rac1 pathway." (PMID 32669966, 2020). "3D cultures established from HCC1954 breast cancer cells treated with a small molecule Rac1 inhibitor had reduced pSer727 STAT3 levels and inhibited invasion." (PMID 32915198, 2020). "They found that the expression of either the Rac1 or Rac2 mutant protein resulted in enhanced colony formation in soft agar and tumor formation and growth in mice, confirming the transforming capabilities of Rac1 and Rac2 in breast cancer." (PMID 32992837, 2020). "When analyzing the correlation of Rac1 expression with different subtypes of breast cancer, we discovered that the TNBC patients with high Rac1 level had the worst DFS and OS." (PMID 32193458, 2020). "1A-116 Rac1 inhibitor showed antitumoral activity in vitro on a wide variety of cancer types such as breast cancer, glioblastoma and acute myeloid leukemia." (PMID 32351958, 2020). "For example, p66ShcA has been reported to activate Rac1, which has important roles in promoting breast cancer cell motility, invasion, and survival." (PMID 31941526, 2020). "It has been shown a direct relationship between Rac1 activation and the metastatic potential of breast cancer cells." (PMID 32351958, 2020). "This group first isolated cDNAs for Rac1, Rac2 and Rac3 genes from various breast cancer cell lines and performed Sanger sequencing on them." (PMID 32992837, 2020). "Another study showed that heregulin, a ligand for Erb3 and Erb4 receptors, sensitizes breast cancer cells for CXCL12 mediated Rac1 activation." (PMID 33096815, 2020). "Overall our data indicate that ZNF750 acts as tumour suppressor gene in breast cancer by negatively regulating the expression of RAC1." (PMID 33298895, 2020). "In support of Rac1 function in breast cancer, studies have also shown that Rac3 activation promotes invasion." (PMID 32992837, 2020). "Research in our lab utilizing microRNAs supports the oncogenic effect of Rac1 on breast cancer cell migration." (PMID 32992837, 2020). "As with breast cancer, chemical Rac1 inhibition impedes STAT3 activation and blocks epithelial-mesenchymal transition (EMT) in CRC." (PMID 32915198, 2020). "Studies have shown that Rac1 activation is critical for resistance to trastuzumab in HER2+ breast cancer cells with upregulated insulin growth factor receptor (IGFR)." (PMID 32322580, 2020). "Zhao and colleagues found that Rac1 is highly activated in trastuzumab-resistant SKBR3 breast cancer cells." (PMID 32992837, 2020). "Recent study found RAC1 pathway was activated in the regulation of breast cancer cell response to IR is to induce G2/M checkpoint activation." (PMID 32411607, 2020). "We have recently found that RAC1 was upregulated after ZNF750 depletion in breast cancer cell lines." (PMID 33298895, 2020). "Two separate studies demonstrated that subjecting breast cancer cells to IR resulted in the immediate increase of Rac1." (PMID 32992837, 2020). "The metabolite of azathioprine, 6-Thio-GTP, also inhibits Vav-mediated activation of Rac1, as reported from breast cancer cells and lymphocytes." (PMID 32322580, 2020). "We reported an anthraquinone compound, Rhein, and its derivative, 4F, and investigated their downregulation effects on Rac1 in breast cancer cells in vitro." (PMID 32547389, 2020). "All together, these data show that enhanced Rac1 activation promotes breast cancer migration and invasion." (PMID 32992837, 2020). "In triple negative breast cancer cell lines, Vav2 was shown to interact with NEDD9, a scaffolding protein involved in cell migration and thus, activate Rac1 in breast cancer cell lines." (PMID 32322580, 2020).
breast carcinoma (continued). "Altogether, our findings demonstrate that targeting Rac1 is a potential strategy to overcome acquired chemoresistance in breast cancer." (PMID 32193458, 2020). "At the same time, elevated levels of Rac1 have been detected in multiple types of malignancies (e.g., gastric cancer, lung cancer, oesophageal cancer, breast cancer, hepatocellular cancer, gallbladder cancer, and ovarian cancer)." (PMID 32731493, 2020). "Collectively, these data suggest that ZNF750 controls the expression of RAC1 in breast cancer cell lines." (PMID 33298895, 2020). "On the other hand, β2-chimaerin abrogated Rac1 activation by HRG in MCF-7 breast cancer cells, as we have reported in a previous study." (PMID 32092966, 2020). "Our clinical studies discovered that high Rac1 expression was correlated with poor outcome to neoadjuvant treatment in the breast cancer patients." (PMID 32193458, 2020). "In breast cancer, Vav2 activates Rac1/3 to regulate actin polymerization, invadopodia extension, matrix degradation, vesicular trafficking, and invasion." (PMID 32322580, 2020). "Using an insertional mutagenesis screen followed by 3′ rapid amplification of cDNA ends (RACE), Goka and Lippman found a different mechanism that leads to Rac1-mediated transformation in breast cancer." (PMID 32992837, 2020). "We recently described a novel Caveolin-1(CAV1)/Ras-related protein 5A (Rab5)/Ras-related C3 botulinum toxin substrate 1 (Rac1) signaling axis that promotes metastasis in melanoma, colon, and breast cancer cells." (PMID 31484460, 2019). "Our previous study demonstrated that hypoxia-induced HIF-1α expression in breast cancer cells involves a cascade of signaling events, including Rac1 activation." (PMID 31462898, 2019). "Several studies, including ours, demonstrated that RAC1 GTPase is upregulated/hyperactivated in breast cancer cells (in all three subsets like luminal, HER2-enriched, and TNBC) and is associated with poor prognosis." (PMID 31027363, 2019). "Overexpression of RAC1 is involved in multiple human cancers such as breast cancer and liver cancer." (PMID 31779616, 2019). "HACE1 preferentially catalyzes polyubiquitination of GTP-bound Rac1 at Lys147 and decreases Rac1 protein levels in breast cancer cells." (PMID 31248165, 2019). "Among these, phosphatidylinositol 3-kinase (PI3K) and the small GTPase-Rac1 signaling have been reported to promote actin organization of breast cancer cells in response to TGF-β." (PMID 30970018, 2019). "To find the relevance of the NUMB, TCF7, and LEF1 promoters to β-catenin/RAC1, we performed a ChIP assay using anti-β-catenin/anti-RAC1 antibody in both colon and breast cancer chromatin samples." (PMID 30650643, 2019). "The first evidence of the critical and distinct implication of Rac3 on the invasive behavior of breast carcinoma cells and glioblastoma cells has been obtained by silencing the expression of either Rac3 or Rac1 by RNA interference." (PMID 31514269, 2019). "Previously, we reported that KRT19 binds to the β-catenin/RAC1 complex in breast cancer cells, and another research group found that RAC1 plays vital roles in β-catenin localization." (PMID 30650643, 2019). "P120 catenin (p120), a Src substrate that can indirectly activate Rac1 and Cdc42, acts as an obligate intermediate between ErbB2 and Rac1/Cdc42 to modulate the metastatic potential of breast cancer cells." (PMID 30754684, 2019). "Here, we report that the Rho GTPase activators Vav2 and Vav3 utilize a new Rac1-dependent and miR-200c-dependent mechanism that maintains the epithelial state by limiting the abundance of the Zeb2 transcriptional repressor in breast cancer cells." (PMID 30087437, 2019). "Together, these observations support the notion that inhibiting protein SUMOylation abrogates the migratory and invasive capacity of breast cancer cell lines by inhibiting RAC1 SUMOylation." (PMID 31578236, 2019).
breast carcinoma (continued). "Previous studies showed that salubrinal reduces proliferation and migration of breast cancer cells in a murine model of mammary tumor by eIF2α-mediated suppression of Rac1 GTPase18." (PMID 31801950, 2019). "Hypoxia treatment in breast cancer cells led to the activation of Rac1 in a time-dependent manner, as determined with the pulldown assay." (PMID 31462898, 2019). "Previous reports have shown that hypoxia-induced breast cancer cell motility is Rac1 dependent and the Rac1 activity is driven by HIF-1α-mediated transcriptional induction of CXCR4." (PMID 31462898, 2019). "The study highlights a potential role for ARF6 in linking EGF-receptor signaling to Rac1 recruitment and activation at the plasma membrane to promote breast cancer cell directed migration." (PMID 28524754, 2019). "Data obtained from different cell lines including pancreatic ductal epithelial cells and highly metastatic human breast carcinoma cells revealed that Rac1 and RAC1B can significantly modulate TGF-β1-induced cell migration." (PMID 30621237, 2019). "The loss of expression of RAC1 ubiquitin ligase, HACE1 E3 ligase, induces RAC1 hyperactivation and contributes to the RAC-mediated tumor progression in breast cancer." (PMID 31248017, 2019). "In breast cancer cells, both nuclear RAC1 and β-catenin levels decreased upon KRT19 knockdown, which supports the evidence that RAC1 directly regulates β-catenin nuclear translocation." (PMID 30650643, 2019). "Our results demonstrate that low Pxn phosphorylation levels at Ser 83, consequent to the reduced CD1/Cdk4 functional interaction, led to inhibition of Rac1-activity, as evidenced by the decrease of pSer144-Pak1 levels, in all breast cancer cell lines tested." (PMID 31426542, 2019). "In this current study, we conducted co-immunoprecipitation (Co-IP) and found that KRT19 interacts with β-catenin alone in colon cancer cells and with the β-catenin/RAC1 complex in breast cancer cells." (PMID 30650643, 2019). "We chose to study the expression of β1 integrin and Rac1 in breast cancer cell lines and IMPC and correlated our findings with the clinicopathologic features of patients." (PMID 29435106, 2018). "ARHGAP15 is therefore considered to suppress migration of breast carcinoma cells by inactivating Rac1." (PMID 29534468, 2018). "Rac1, RhoA, and RhoC are commonly overexpressed in human breast cancers and RNAi-mediated knockdown or deletion of these genes inhibits tumorigenesis and metastasis." (PMID 29769144, 2018). "More recently, a mechanistic link between PI3K and MEK/Erk via P-Rex1/Rac1/c-Raf has been reported in breast cancer cells." (PMID 29983884, 2018). "In human epidermal growth factor receptor 2 (HER2)-positive breast cancer cells, two distinct mTORC2-dependent pathways converge on Rac1, either through Akt-Tiam1 or through PKC-RhoGDI2." (PMID 30544910, 2018). "We found that GAS7 was associated with CYFIP1 and WAVE2 complex to suppress breast cancer metastasis via blocking CYFIP1 and Rac1 protein interaction, actin polymerization, and β1-integrin/FAK/Src signaling." (PMID 29706651, 2018). "Alternatively, the Rac1 GEFs P-Rex1, Vav2/3, and Dock1 have been shown to contribute to metastatic behavior in particular breast cancer subtypes." (PMID 29769144, 2018). "HRG is known to induce Rac1 activation and subsequent phosphorylation of p21 (RAC1)-activated kinase 1 (PAK1), a critical effector protein of Rac1 signaling, in breast cancer cells." (PMID 29534468, 2018). "The most prominent role for P-Rex1 in breast cancer cells is the control of motility signaling via Rac1, a crucial step for metastatic dissemination." (PMID 29983884, 2018). "For example, the Rac1 GEFs P-Rex1 and Vav2/3 contribute to metastasis in luminal subtype breast cancers, while the Rac1 GEF Dock1 controls metastasis in HER2-positive breast cancers." (PMID 29769144, 2018).
breast carcinoma (continued). "NMac1-treated MDA-MB-231 breast cancer cells showed dramatic changes in morphology and actin-cytoskeletal organization following inhibition of Rac1 activation." (PMID 30026594, 2018). "Because of the finding that NMac1 treatment induces Rac1 inhibition and reorganization of actin cytoskeleton, we examined the migration and matrigel invasion of in vitro breast cancer cell lines in response to NMac1." (PMID 30026594, 2018). "Overall, these results suggest that GAS7 associates with CYFIP1 to perturb the binding of CYFIP1 and active form of Rac1, thus resulting in the inhibition of actin polymerization in breast cancer cells." (PMID 29706651, 2018). "For example, heregulin stimulation of ErbB3 and ErbB4 causes upregulation of C-X-C chemokine receptor type 4 (CXCR4) and increases Rac1 activation through a stromal cell-derived factor (SDF)-1-CXCR4 mediated PREX1 GEF mechanism in breast cancer cells." (PMID 30261690, 2018). "Two different Rac1 inhibitors displayed anti-angiogenic activity in breast cancer models in vivo supporting a potential benefit of Rac1 inhibition as an alternate anti-angiogenic strategy in cancer, including ovarian cancer." (PMID 30261690, 2018). "TNFAIP2 regulates the actin cytoskeleton, especially the membrane protrusions, to promote cell migration and invasion by regulating the activity of the small GTPase Cdc42 and Rac1 in breast cancer and nasopharyngeal carcinoma." (PMID 30145807, 2018). "ELMO1 is associated with metastasis in several cancers, and is part of the chomokine regulated pathway, including Rac1 and Rac2, that regulates the actin cytoskeleton in metastatic breast cancer." (PMID 30557297, 2018). "In mammary tumor explants expressing activated Neu/ErbB-2 receptor, the Rac1/Cdc42-GAP, CdGAP, was required for TGFβ1 to induce migration and invasion." (PMID 29415466, 2018). "Inhibition or inactivation of RAC1 decreases estrogen receptor levels, and in PTEN-deficient and insulin-like growth factor I receptor-overexpressing human breast cancer SKBR3 cells reduces Trastuzumab resistance." (PMID 28499439, 2017). "In breast cancer cells with both Her2 amplification and PIK3CA mutations, treatment with a pan-PI3K inhibitor GDC0941 led to reduced AKT and Rac1/ERK activity." (PMID 27845911, 2017). "Rictor/mTORC2-dependent dampening of the endogenous Rac1 inhibitor RhoGDI2, a factor that correlated directly with increased overall survival in HER2-amplified breast cancer patients, promoted Rac1 activity and tumor cell invasion/migration." (PMID 28666462, 2017). "We further show in two breast cancer cell lines that Rac1 and Rac1b are powerful modulators of TGF-β1-induced random cell migration, whereby Rac1 promotes and Rac1b inhibits random cell migration." (PMID 28726720, 2017). "In previous reports, ZINC69391 was able to inhibit several Rac1-GEF interactions, which were associated to antiproliferative effects, cell cycle arrest and migration inhibition of highly aggressive breast cancer cell lines." (PMID 29228706, 2017). "Loss of the E3 ubiquitin ligase HACE1 results in enhanced RAC1 signaling contributing to breast cancer progression while eIF2α-mediated downregulation of RAC1 signaling attenuates malignant phenotypes of breast cancer cells." (PMID 28499439, 2017). "Inhibition of Rac1 by ZINC69391 was also associated with reduced epidermal growth factor (EGF)-mediated Rac1 activation and efficient inhibition of cell proliferation, cell cycle progression and cell migration in highly metastatic breast cancer cell lines." (PMID 27442895, 2017). "We also found that the WVLGE-containing polypeptide has a Rac1-dependent potential to suppress breast cancer growth in vitro and in vivo." (PMID 28549350, 2017). "Data from our and other studies point to signaling crosstalk between TGF-β and RAC1 and the related isoform, RAC1b, in pancreatic and mammary carcinoma cells." (PMID 28499439, 2017).